OCIAD1 (OCIA domain containing 1)
Description:
Maintains stem cell potency (By similarity). Increases STAT3 phosphorylation and controls ERK phosphorylation (By similarity). May act as a scaffold, increasing STAT3 recruitment onto endosomes (By similarity). Involved in integrin-mediated cancer cell adhesion and colony formation in ovarian cancer.
Synonyms: ASRIJ; OCIA; FLJ20455; TPA018
Tractability: PROTAC: ubiquitination databases record sites on it; its protein half-life has been measured.
Gene: Protein-coding gene on chromosome 4 (48,805,141 to 48,862,342, forward strand). Ensembl gene ENSG00000109180.
Subcellular location: Endosome
Subcellular location (Human Protein Atlas): Vesicles
Gene Ontology:
Molecular function: protein binding
Biological process: endocytosis; hematopoietic stem cell homeostasis; positive regulation of receptor signaling pathway via JAK-STAT; regulation of stem cell differentiation
Cellular component: membrane; mitochondrion; endosome; Golgi apparatus; lysosome
Genetic constraint (gnomAD): Loss-of-function variants: 5 observed, 9.49 expected, observed/expected ratio (o/e) 0.53, 90% interval 0.27 to 1.11. That is too few expected variants to judge how well the gene tolerates losing a copy. Missense variants: 53 observed, 53.68 expected, observed/expected ratio (o/e) 0.99, 90% interval 0.79 to 1.24. Synonymous variants: 22 observed, 18.22 expected, observed/expected ratio (o/e) 1.21, 90% interval 0.86 to 1.71.
Homologues: Orthologues: chimpanzee OCIAD1 (99% identical), macaque OCIAD1 (98% identical), dog OCIAD1 (93% identical), guinea pig OCIAD1 (92% identical), pig OCIAD1 (92% identical), rabbit OCIAD1 (91% identical), mouse Ociad1 (86% identical), rat Ociad1 (83% identical), tropical clawed frog ociad1 (49% identical), zebrafish ociad1 (45% identical), Drosophila melanogaster asrij (31% identical). Paralogues in human: OCIAD2 (20% identical).
Diseases named in the same sentence as OCIAD1 in open-access papers:
OCIAD1 is named in the same sentence as 17 diseases in open-access papers, as found by Europe PMC text mining. Sharing a sentence is not in itself a finding about the gene and the disease. The quoted sentences say what the papers report.
ovarian carcinoma (7 papers, 2018 to 2024). A malignant neoplasm originating from the surface ovarian epithelium. "OCIAD1 has been implicated in several pathological conditions including ovarian carcinoma, myelodysplastic syndromes, and mitochondrial disorders." (PMID 34295888, 2021). "OCIAD1 encodes a poorly characterized predicted transmembrane protein that is aberrantly expressed in ovarian carcinomas and implicated in the regulation of mitochondrial metabolism via Complex I." (PMID 34034859, 2021). "The Ovarian Carcinoma Immunoreactive Antigen domain (OCIAD) - containing proteins OCIAD1/Asrij and OCIAD2, are implicated in several cancers and neurodegenerative diseases." (PMID 29743632, 2018). "Metabolic associations with genes known to associate with bladder cancer (BLCAP), ovarian cancer (OCIAD1), and infertility caused by azoospermia (DAZAP1) could highlight the importance of integrating both methylation and metabolomics for assessing T2D complications." (PMID 37679740, 2023). "Intriguingly, recent research identified a protein (ovarian cancer immuno‐reactive antigen domain containing 1 [OCIAD1]), that can specifically control levels of TIMM17A‐containing TIM23 (unpublished data)." (PMID 38837610, 2024). "We identified ovarian carcinoma immunoreactive antigen domain-containing protein 1 (OCIAD1), a poorly characterized protein, as a key regulator of Complex III biogenesis." (PMID 34034859, 2021). "Here, we describe ovarian cancer immunoreactive antigen domain containing protein 1 (OCIAD1) as a further substrate identified by this approach." (PMID 32697788, 2020). "OCIAD1 was first identified by immunoscreening of an ovarian carcinoma cDNA expression library with ascites fluid from patients with ovarian cancer." (PMID 32697788, 2020). "Overexpression of OCIAD1 in the presence of lysophosphatidic acid induced cell adhesion to collagen and laminin in human ovarian cancer cell lines." (PMID 30558204, 2018). "By cleaving and thereby inactivating selected host factors it also plays a role in the persistence and pathogenesis of hepatitis C. Here, we describe ovarian cancer immunoreactive antigen domain containing protein 1 (OCIAD1) as a novel cellular substrate of the HCV NS3-4A protease." (PMID 32697788, 2020). "This supports the hypothesis that OCIAD1 may upregulate metastatic potential via Jak/STAT regulation in human ovarian cancer." (PMID 30558204, 2018).
Alzheimer disease (2 papers, 2020 to 2025). A progressive, neurodegenerative disease characterized by loss of function and death of nerve cells in several areas of the brain leading to loss of cognitive function such as memory and language. "In silico analysis combined with experimental data from patients with AD and mouse models linked increased levels of Asrij/OCIAD1 to brain aging and Alzheimer’s disease." (PMID 41143250, 2025). "While little is known about the function of OCIAD1, a homolog designated as OCIAD2 has been identified as a modulator of γ-secretase, an enzyme that stimulates the production of amyloid β in the early stage of Alzheimer’s disease." (PMID 32697788, 2020).
breast carcinoma (1 paper, 2020). "However, other strong relationships in MR, such as the associations between the cis-regulation of OCIAD1 with stroke (per 1 SD OR: 0.87, 95% CI: 0.82–0.91, Pcausal = 1.54 × 10−7) and breast cancer (per 1 SD OR: 0.78, 95% CI: 0.71–0.86, Pcausal = 1.25 × 10−6), were not mapped by previous GWAS." (PMID 32358504, 2020).
cervical cancer (1 paper, 2022). A primary or metastatic malignant neoplasm involving the cervix. "In addition, we examined the mRNA expression of RNF4, OCIAD1, TMED5, DHX15, MED28, and LETM1 in TMEM33 knockdown cervical cancer cells." (PMID 35832191, 2022).
chronic hepatitis B (1 paper, 2020). "Importantly, we also found cleavage of OCIAD1 in liver biopsies from patients with chronic hepatitis C. Liver biopsy samples from 5 patients with chronic hepatitis C and two patients with chronic hepatitis B as controls were analyzed by immunoblot using a monoclonal antibody (mAb) against OCIAD1." (PMID 32697788, 2020).
chronic hepatitis C (1 paper, 2020). "Both full-length and cleaved forms of OCIAD1 were detected in liver biopsy specimens from patients with chronic hepatitis C whereas only the full-length protein was detected in the controls." (PMID 32697788, 2020). "Cleavage was observed in heterologous expression systems, the replicon and cell culture-derived HCV systems, as well as in liver biopsies from patients with chronic hepatitis C. NS3-4A proteases from diverse hepacivirus species efficiently cleaved OCIAD1." (PMID 32697788, 2020). "The percentage of OCIAD1 cleavage varied widely among the 5 patients with chronic hepatitis C, ranging from 0 to 45% and correlating roughly with the serum viral loads as well as the percentage of MAVS cleavage previously observed in the same biopsy specimens." (PMID 32697788, 2020).
hepatitis C (1 paper, 2020). "Hence, investigating a potential role of OCIAD1 and its cleavage in the pathogenesis of hepatitis C will require experimental models which are still limited to date." (PMID 32697788, 2020). "Our results did not reveal any impact of OCIAD1 or its cleavage on the entire viral life cycle in the HCVcc system in vitro, raising the possibility that OCIAD1 may be involved in the pathogenesis of hepatitis C in vivo." (PMID 32697788, 2020). "Overexpression as well as knock down and rescue experiments did not affect the HCV life cycle in vitro, raising the possibility that OCIAD1 may be involved in the pathogenesis of hepatitis C in vivo." (PMID 32697788, 2020). "Finally, OCIAD1 appears not to be involved in the viral life cycle in vitro, raising the possibility that NS3-4A-mediated cleavage of OCIAD1 may play a role in the pathogenesis of hepatitis C in vivo." (PMID 32697788, 2020). "Finally, OCIAD1 did not affect the HCV life cycle in vitro, raising the possibility that OCIAD1 and its cleavage may play a role in the pathogenesis of hepatitis C in vivo." (PMID 32697788, 2020).
prostate carcinoma (1 paper, 2020). A carcinoma that arises from epithelial cells of the prostate gland. "Consistently, we found that genetically predicted higher expression of OCIAD1 in the blood was associated with an increased lifespan and a reduced risk of breast and prostate cancers." (PMID 32358504, 2020).
cancer (6 papers, 2011 to 2025). A tumor composed of atypical neoplastic, often pleomorphic cells that invade other tissues. "Mammalian Asrij (Ociad1) is expressed in stem cells of the blood vascular system and is implicated in several cancers." (PMID 22110713, 2011). "Changes in Ociad1 expression levels can modulate integrin function thereby affecting cell adhesion and the ability of cancer cells to form secondary colonies." (PMID 22110713, 2011). "Moreover, the TMEM33 expression level was remarkably positively correlated with similar genes of RNF4, OCIAD1, TMED5, DHX15, MED28 and LETM1, which have been reported to be implicated in tumorigenesis of various cancers." (PMID 35832191, 2022). "OCIAD1 has been shown to regulate energy metabolism in human pluripotent stem cells and suppression of OCIAD2 led to a reduction in mitochondria and the downregulation of cellular growth in cancer cell lines." (PMID 39364696, 2025). "The expression levels of LIAS had a positive correlation with the expression levels of CTD-2366F13.1 (R = 0.47, p < 0.001), RAD17 (R = 0.48, p < 0.001), OCIAD1 (R = 0.49, p < 0.001), PACRGL (R = 0.49, p < 0.001), MRPS27 (R = 0.49, p < 0.001), and THAP9 (R = 0.49, p < 0.001) in pan-cancer." (PMID 35982953, 2022).
OCIAD1 also shares sentences with these, for which no sentence is quoted: neurodegenerative disease (2 papers); Azoospermia (1); bladder cancer (1); infection (1); Infertility (1); myelodysplastic syndrome (1); myeloproliferative disorder (1); Stroke (1).